IL10 (interleukin 10)
Diseases named in the same sentence as IL10 in open-access papers (continued):
Sharing a sentence is not in itself a finding about the gene and the disease.
visceral leishmaniasis (continued). "In agreement with our results, the in vitro supplementation with ATRA of PMBC (Treg and monocytes) from humans infected with L. infantum reduced the expression of IL-10, indicating a possible regulatory role of vitamin A (down modulate) in the production of IL-10 in visceral leishmaniasis." (PMID 34573521, 2021). "The lack of correlation between FoxP3+ and IL-10+ cells suggests that other regulatory cells could be the source of IL-10, since it has been described that IL-10-producing CD25− Foxp3− T cells are involved in the pathogenesis of visceral leishmaniasis." (PMID 29743809, 2018). "We and others previously demonstrated that IL-10 could contribute to parasite survival, and a correlation between IgG levels and IL-10 production was identified in visceral leishmaniasis." (PMID 27631090, 2016). "In addition, the density of IL10-producing cells was higher in the spleen of the patient with visceral leishmaniasis." (PMID 25200768, 2014). "Visceral leishmaniasis cases also exhibited an increase in their anti-inflammatory and regulatory cytokine patterns, as shown by the higher amounts of IL-4, and particularly IL-10 (P <0.0001)." (PMID 24886212, 2014). "It has been reported that IL-10 limits parasite burden in murine Trypanosoma cruzi infection, and IL-10 mRNA levels directly correlate with parasite load in lesions tissues of post kala azar dermal leishmaniasis patients." (PMID 24146978, 2013). "In the course of the chronic stimulation of Th1 and other T cell subsets seen in human and murine diseases such as visceral leishmaniasis, there is induction of IL-10 production by the IFN-γ producing T cell and subsequent down regulation of Th1 differentiation." (PMID 22545169, 2012). "Importantly, a study with splenic aspirates from visceral leishmaniasis (VL) patients demonstrated that blockade of IL-10 enhanced control of the parasites, which provides the experimental foundation for a host-directed therapy where IL-10 would be blocked in VL patients." (PMID 33841444, 2021). "Indeed, while aTregs (Foxp3− Tregs) are known to be the major producers of IL-10 in filarial infections 21 and visceral leishmaniasis 22, Th1 cells are an important source of IL-10 in others, including malarial, infections 23, and in animal models of toxoplasmosis 24 and cutaneous leishmaniasis." (PMID 26417443, 2015). "The exacerbated profile of pro- and anti-inflammatory cytokines in patients with kala-azar appears related to disease worsening, particularly in the levels of IFN-γ, IL-6, IL-8, and IL-10." (PMID 41003560, 2025). "We employed ROC curve analysis to thoroughly assess the potential of IL-1β, IL-6, IL-8, IL-10, IL-12, and TNF-α as predictive biomarkers for identifying fatal cases of kala-azar." (PMID 41003560, 2025). "In Sudan, individuals with kala-azar have high levels of IFN-γ, TNF-α, IL-4, IL-6, IL-10, IL-12, and IL-17A." (PMID 41003560, 2025). "In addition, infection control in visceral leishmaniasis has been related to a Th1-type immune response, in which the pro-inflammatory cytokines IFN-γ/TNF must overcome the effects of the regulatory cytokine (IL-10), while susceptibility is related to a deficient pro-inflammatory response." (PMID 39771984, 2024). "It has been evidenced that this protein elicits IL-4 and IL-10 expression, and it also suppresses IL-12 and IFN-γ expression in blood-derived monocytes from patients with visceral leishmaniasis." (PMID 35634280, 2022). "The present results suggest that IL-10, IFN-γ, and TGF-β1 can be used as markers of active visceral leishmaniasis." (PMID 34351903, 2021). "While IL-10 plays an important role in down regulating Th1 immune response, decreasing lymphocyte proliferation and production of IFN-γ in patients with visceral leishmaniasis, the role of IL-10 in the pathogenesis of TL is not so clear." (PMID 23060880, 2012).
visceral leishmaniasis (continued). "Even in non-severe kala-azar, we identified that levels of IL-6, IL-8, and IL-10 are promising biomarkers of early response to treatment." (PMID 41003560, 2025). "Thus, here we characterized the production of IL-10, as well as the expression of CD39 and CD73 exhibited by Treg cells aiming to better understand the role of this subpopulation in human visceral leishmaniasis pathology." (PMID 36668925, 2022). "In patients with visceral leishmaniasis, serum vitamin A has been found to be reduced, and an in vitro supplementation with vitamin A in combination with SLA stimulus promoted a reduction of IL-10 in Treg cells and monocytes." (PMID 34573521, 2021). "Different of human CL, it is well known that during active human visceral leishmaniasis, cell-mediated immune responses are suppressed and consequently a decrease in IFN-γ which is related to the production of regulatory cytokines such as IL-10." (PMID 34691019, 2021). "However, although CD4+CD25+ T cells have been related with kala-azar and patients suffering from PKDL, FoxP3-CD4+ T cells were reported to be the key source of enhanced IL-10 mRNA expression in spleen of VL patients." (PMID 26829554, 2016). "IL-10 play a key role in downregulating IFN-γ production in human visceral leishmaniasis, but studies have shown that this cytokine does not alter production of IFN-α in CL and ML patients." (PMID 24485388, 2014). "In a hamster model of visceral leishmaniasis (VL), Osorio and colleagues showed that Leishmania donovani infected macrophages displayed enhanced STAT6 and STAT3 signalling in response to the growth factors FGF2 and IGF1, further enhanced by co-stimulation with IL-4 or IL-10." (PMID 29352310, 2018). "Similar ‘self-regulating’ Th1 cells that co-produce IL-10 and IFN-γ were first identified in the lungs of patients with active pulmonary tuberculosis and have since been observed in mice infected with Toxoplasma gondii and Leishmania major as well as in humans with visceral leishmaniasis." (PMID 24743880, 2014). "An increased density of IL10 and Fox-P3-producing cells was observed in the red pulp, as well as in the follicles and in the marginal zones in comparison with the spleens of the patients without visceral leishmaniasis." (PMID 25200768, 2014). "However, in experimental VL in mice and in human visceral leishmaniasis, IL-10 comes from non-T reg cells (CD4+CD25−FoxP3−), indicating that therapeutic approaches require Leishmania species-specific understanding of the immune response." (PMID 21912560, 2012). "In our study, IL-10 levels in individuals with HIV and kala-azar were almost half of the values found in individuals without HIV, but without statistical significance (p = 0.0551)." (PMID 41003560, 2025). "Our findings indicate that IL-6, IL-8, and IL-10 concentrations were similar in HIV-coinfected and non-HIV-coinfected kala-azar patients (p > 0.05)." (PMID 41003560, 2025). "However, in visceral leishmaniasis, it has been suggested that the impaired function of cellular immunity that correlates with progression of active disease may be due to the inhibitory effects of IL-10 independent of the IFNγ level." (PMID 21912560, 2012). "In comparison with the spleens of the other two patients without visceral leishmaniasis, an increase was observed in the CD4/CD8 ratio and in the number of IL-10- and FoxP3-producing cells, while the number of IL-17-producing cells was lower in the spleen of the patient with visceral leishmaniasis." (PMID 25200768, 2014).
allergic asthma (73 papers, 2004 to 2025). A asthma with a basis in a pathological type I hypersensitivity reaction. "IL-10, a cytokine with anti-inflammatory properties, affects several immune cells implicated in allergic asthma." (PMID 39594470, 2024). "In allergic asthma, where pathological responses to inhaled allergens develop due to a failure in immune tolerance, a successful therapeutic strategy is associated with an increase in IL-10 levels." (PMID 38093354, 2023). "Additionally, IL-10 and IL-1β gene polymorphisms are associated with allergic asthma in children and the association between IL-13 polymorphisms and susceptibility to childhood asthma has been extensively studied." (PMID 36313877, 2022). "Conversely, the production of anti-inflammatory cytokines, for instance, IL10, terminates during the progression of allergic asthma in experimental asthma models and asthmatic individuals." (PMID 38711519, 2024). "In contrast, other studies have suggested that LPS-induced protection against allergic asthma is due to IL-10 release by monocyte-derived alveolar and interstitial macrophages." (PMID 37954159, 2023). "Chronic infection with T. spiralis can mediate protection against allergic asthma by eliciting a regulatory T cell population and increasing IL-10 levels." (PMID 35500031, 2022). "Other than secretion of their signature cytokine IL-9, Th9 cells from mice and humans also secret other cytokines such as IL-10, IL-17, IL-21, and IL-22, to facilitate immune responses in the setting of allergic asthma." (PMID 35757774, 2022). "Patients with allergic asthma and rhinitis show a decrease in the percentage of IL-10-secreting CD19+CD24hiCD27+ Breg cells in response to LPS stimulation." (PMID 34867940, 2021). "This condition in the lung corroborates with authors that describe the imbalance between the IL-10-induced anti-inflammatory response and the pro-inflammatory response in healthy individuals as well as in mice from the Basal group in model allergic asthma." (PMID 35185864, 2021). "The proportion of Breg cell subsets within B cells was found to be lower in patients with allergic rhinitis and allergic asthma, and allergen immunotherapy enhanced the frequency of IL-10-producing antigen-specific B cells." (PMID 34959429, 2021). "The results indicate that none of all the tested therapeutic strategies showed the potential to counteract the development of allergic asthma by increasing the production of IL-10 by CD4+ T cells other than Treg ones." (PMID 34071080, 2021). "Adoptive transfer of Breg cells was shown to normalize airway inflammation and lung function in a murine model of allergic asthma in an IL-10-dependent manner." (PMID 34959429, 2021). "Very recently, IL-10-producing KLRG1+ ILC2s emerged as other hypothetically interesting candidates for therapeutic cell transfer in the context of allergic asthma therapy." (PMID 34177944, 2021). "Another surprising finding about IL-10 role in allergic asthma, is the induction of airway fibrosis through IL-13/STAT6 pathway or increased TGF-β production, with mucus hypersecretion." (PMID 32024540, 2020). "The level of IL-10 was found to be reduced significantly in T cells of peripheral blood during the onset of allergic asthma." (PMID 30294594, 2018). "There is evidence in different models that enhanced activity of Bregs producing IL-10 strongly suppresses inflammatory processes, and conversely, Van Der Vlugt reported that patients with allergic asthma displayed B cells with impaired regulatory activity." (PMID 30622536, 2018). "Patients with allergic asthma harbor a defective expansion of such IL-10–producing B cells in response to lipopolysaccharide (LPS) stimulation and a weaker IL-10 response to house dust mite (HDM) allergen–activated T cells." (PMID 30622536, 2018). "The present study focusses on the role of miR-98 in the regulation of IL-10 expression in B cells of patients with allergic asthma." (PMID 28760845, 2017).
allergic asthma (continued). "During allergic asthma, Tregs seem to play a beneficial role by inhibiting Th2 responses and regulating B-cell antibody production, mainly through the secretion of IL-10 and transforming growth factor beta (TGF-β)." (PMID 28066430, 2016). "High levels of IL-10 induced by Smteg inoculation shed light to a possible mechanism of modulation induced by schistosomula tegument in allergic asthma." (PMID 27454771, 2016). "The possible role of IL-10 as a therapy in allergic asthma has already been suggested, but the divergent roles of this suppressor molecule in the antiviral immune response raise concerns." (PMID 25430775, 2015). "When individuals with allergic asthma are exposed to immunotherapy treatment, an increase in IL-10 occurs during the first months of treatment." (PMID 24236015, 2013). "But the role of IL-10 in allergic asthma and therefore new treatment possibilities needs to be further elucidated." (PMID 22855687, 2012). "The presence of PS-G in an allergen pulse promoted allergic MD-DCs to produce IL-12 p70, IL-12 p40, IL-6, IL-23, and IL-10, and exerted an effect on shifting the immune balance towards Th1 in children with allergic asthma." (PMID 21612588, 2011). "Besides that, IL-10-secreting B cell subsets, namely regulatory B cells (Bregs), are reported in mice and humans to play a role in allergic asthma." (PMID 38172451, 2024). "Low levels of IL-10 or few M2b macrophages may be involved in regulating macrophage metabolism and promoting the development of allergic asthma." (PMID 38646478, 2024). "Furthermore, intranasal delivery of mesenchymal stem cell-derived exosomes increases the proportion of IL-10-producing interstitial macrophages in the lungs, exerting anti-inflammatory effects and effectively treating allergic asthma." (PMID 38655063, 2024). "Although the accumulation of macrophages is prerequisite for emphysema, however, in allergic asthma, depletion of alveolar macrophage reversed the immunosuppressive effect of MSCs in which the production of IL-10 was dependent on the presence of alveolar macrophage." (PMID 33436065, 2021). "In addition, P. cocos extract markedly suppressed Th2cytokines, IL-4, IL-5, and IL-10, secretions that have been suggested as a potential therapeutic target in allergic asthma." (PMID 33919400, 2021). "Therefore, in children with allergic asthma, Treg populations are suppressed, and the expression of cytokines such as IL-10 and TGF-β are also significantly reduced." (PMID 32834826, 2020). "The children with allergic asthma have a lower level of serum IL-10 and higher level of TGF-β." (PMID 30294594, 2018). "IL-10 exhibits a direct inhibition effect on airway inflammatory cell activation, releases inflammatory factor in asthmatic patients, can inhibit the IgE production, promotes IgG4 synthesis, and plays an important role in pathophysiology of allergic asthma." (PMID 29713367, 2018). "As a result, the modulation of gut microbiota by PHF may subsequently lead to the immune-modulation of Tfh and Tfr cells, as evidenced by the increased serum IL-10, to suppress the allergic inflammation in allergic asthma." (PMID 30373169, 2018). "IL-10 regulates allergic asthma and is directly involved in the regulation of inflammatory cells." (PMID 30294594, 2018). "Increased secretion of PGE2 and IL-10 by EPA-stimulated MSCs may also help resolve the inflammatory process in HDM-induced allergic asthma." (PMID 29881388, 2018). "However, the detailed mechanism regarding how IP-AhR axis down-regulates IL-10 expression in DCs and its detailed mechanisms on the regulation of allergic asthma await further in-depth studies." (PMID 29581487, 2018). "For example, the larval ES products of T. suis have immunomodulatory functions and could prevent OVA-induced allergic asthma in a IL-10 dependent manner." (PMID 28494800, 2017).
allergic asthma (continued). "Because IL-10 is involved in controlling allergic asthma and its production could be promoted by statins, we assessed the IL-10 concentration in lung homogenates." (PMID 28066430, 2016). "The possible role of IL-10 as a therapy in allergic asthma has already been suggested." (PMID 25430775, 2015). "We thus speculate that E. granulosus infection may decrease the severity of allergic asthma by enhancing IL-10 expression and down-regulating the expression of IL-17A." (PMID 25409540, 2014). "Notably, asthmatic patients exhibit reduced IL-10 production compared with healthy individuals, suggesting that therapies aimed at enhancing IL-10 in the lungs may provide a novel approach to controlling allergic asthma." (PMID 40627441, 2025). "Since it was already shown that Bcl-3 is a negative regulator for IL-10, these results indicate that Bcl-3 is a critical inhibitor of IL-10 in allergic asthma and targeting the Bcl-3/IL-10 axis may be a promising approach for allergic asthma therapy." (PMID 38172451, 2024). "Hence, this suggests that improving the population and function of IL10-secreting Tregs may serve as a promising therapy in patients with allergic asthma." (PMID 38711519, 2024). "Our study adds that DMF reduces inflammation in OVA-induced allergic asthma through increased production of IL10 along with an elevated population of Tregs, which may lead to a diminished population of infiltrating pro-inflammatory cells in the lung tissue and BALF." (PMID 38711519, 2024). "IL-22 has been shown to contribute to allergic asthma during the sensitization phase and to promote lung immunopathology during fungal allergy, but it can also inhibit antigen-induced eosinophil airway inflammation through inhibition of IL-25, of IL-10, or during the challenge phase." (PMID 25860963, 2015). "Thus, the induction of Tr1 cells and therefore IL-10 might be a new therapeutical aim in the treatment of allergic asthma since Tr1 cells inhibit airway hyperresponsiveness, amongst other features of allergic asthma." (PMID 22855687, 2012). "Although we were not able to test the suppressive capacity of OVA-loaded alveolar Mφ in our mouse model, targeting of allergens to alveolar Mφ could still be promising to induce immunosuppressive effects in humans, because alveolar Mφ from patients with allergic asthma produce IL-10." (PMID 15538945, 2004). "Based on this, we investigated the efficacy and mechanism of SXCF in allergic asthma by combining inflammatory factors such as TNF-α, IL-4, IL-10, IFN-γ, serological indicators, behavioural results, and pathological results." (PMID 36937885, 2023). "Compared to healthy children of the same age, the allergic asthma patients exhibited significantly increased IL-17 and IL-6 expression levels and a marked decline in TGF-β and IL-10 expression levels." (PMID 32834826, 2020). "Despite the high efficacy of AOS, little is known about the changes of IL-10, TGF-β, Th1, and Th2 cytokines, and CD4+CD25highCD127low Treg cells in the children with allergic asthma." (PMID 30294594, 2018). "In accordance with our results, previous studies showed the therapeutic potentials of helminths in resistance from allergic asthma via the expansion of CD4+CD25+FOXP3+ regulatory cells and IL-10 and TGF-β production." (PMID 28494800, 2017). "We also evaluated the production of cytokines (IL-12 p40, IL-12 p70, IL-6, IL-23, and IL-10) in MD-DCs from allergic asthma children, and found that PS-G alone stimulated Der p 1-pulsed DCs to secrete IL-12 p40, IL-12 p70, IL6, IL23, and IL-10." (PMID 21612588, 2011). "This study aims to explore the therapeutic effect of the airway gene transfer of IL-12, IL-10 and TGF-β on airway inflammation in a mouse model of allergic asthma." (PMID 16677403, 2006).